NEU1 (neuraminidase 1)
Diseases named in the same sentence as NEU1 in open-access papers (continued):
Sharing a sentence is not in itself a finding about the gene and the disease.
diabetes (8 papers, 2020 to 2025). "In diabetes-related contexts, NEU1 deficiency has been shown to be beneficial toward diabetic cardiomyopathy in mice." (PMID 39194692, 2024). "For example, NEU-1 activity is implicated in the development of diabetes due to an enhancement of insulin resistance through insulin receptor desialylation." (PMID 33920466, 2021). "Reported studies have illustrated that the modulation of NEU1 can have profound implications for insulin receptor activation, thereby influencing metabolic pathways critical in conditions such as obesity and diabetes." (PMID 40573316, 2025). "The data in our study suggested that NEU1 inhibition protected against diabetes-induced oxidative damage in vivo and in vitro." (PMID 35002528, 2022). "In the present study, we demonstrated that NEU1 inhibition alleviated deteriorated cardiac function in diabetic hearts, and protected against diabetes-related cardiac fibrosis, inflammation, oxidative damage and cell death in vivo." (PMID 35002528, 2022). "Recent investigations show the role of NEU1 in regulating insulin receptor activity, where its inhibition can enhance insulin signaling, providing a promising intervention for metabolic disorders such as diabetes." (PMID 40573316, 2025). "Therefore, modulating Neu1 translocation to epithelial cell surfaces can be a potential therapeutic strategy for diseases like pulmonary fibrosis and diabetes." (PMID 39128726, 2024). "We have selected Olyra latifolia because in Ivory Coast, their leaves were used for treating diabetes and the diabetic wound and this activity could be related to NEU-1 inhibitory activity." (PMID 33920466, 2021). "Indeed, as the leaves of this plant are used to treat several pathologies such as diabetes, the present work could allow to isolate some active principles targeting NEU-1 and responsible of their medicinal activity." (PMID 33920466, 2021). "As part of the regulatory machinery for energy metabolism and glucose uptake, it is not surprising that NEU1 is pathologically involved in the development of diabetes." (PMID 39194692, 2024). "Sialidase isozyme-selective inhibitors that do not inhibit Neu1 activity may thus be suitable for the treatment of diabetes mellitus." (PMID 32251344, 2020).
hepatocellular carcinoma (8 papers, 2016 to 2024). A malignant tumor that arises from hepatocytes. "Inhibition of NEU1 activity with anti-NEU1 antibody or oseltamivir reduced insulin-stimulated IGF-1R and insulin receptor substrate-1 (IRS-1) phosphorylation in human fibroblasts, and promoted IR-NEU1 association in rat HTC hepatoma cells." (PMID 35479093, 2022). "NEU1 has emerged as a new biomarker for hepatocellular carcinoma (HCC), one of the deadliest malignancies, which lacks diagnostic efficiency." (PMID 39194692, 2024). "NEU-1, therefore, promotes hepatoma cell proliferation and migration which is mediated by the HBc protein, which in return upregulates NEU-1 which is contributing to the HCC development." (PMID 36230790, 2022). "On the other hand, the migration rate decreases after NEU1 knockdown, and is enhanced after its overexpression, in hepatocellular carcinoma cell lines." (PMID 35354905, 2022). "One study aimed to evaluate the role of NEU1 in the activation of signaling pathways and epithelial–mesenchymal transition, and the proliferation and migration of hepatoma cells mediated by HBc protein." (PMID 34948447, 2021). "Through the increase in NEU1 expression, HBc contributes to the activation of downstream signaling pathways and epithelial–mesenchymal transition in HBV-associated hepatoma cells." (PMID 34948447, 2021). "Our results suggests that NEU1 promotes metastasis and proliferation of hepatocellular carcinoma cell lines in vitro, however further research is needed to characterize the tumor-specific role of this gene." (PMID 27602751, 2016). "Furthermore, NEU-1 expression is upregulated in hepatocellular cancer at the mRNA and protein levels in patients, and this sialidase regulates the hepatocellular cancer cells’ proliferation and migration." (PMID 36230790, 2022). "Indeed, hepatitis B’s core protein which is expressed in HBV-infected hepatoma cells increased the NEU-1 expression that contributes to the epithelial–mesenchymal transition." (PMID 36230790, 2022). "Nevertheless, the clinical significance of NEU1 in hepatocellular carcinoma (HCC) has not been fully elucidated." (PMID 34513919, 2021).
pulmonary fibrosis (8 papers, 2017 to 2024). Chronic progressive interstitial lung disorder characterized by the replacement of the lung tissue by connective tissue, leading to progressive dyspnea, respiratory failure, or right heart failure. "Neu1 has also been implicated in the pathogenesis of pulmonary fibrosis, a progressive and often fatal lung disease." (PMID 38500102, 2024). "In idiopathic pulmonary fibrosis and bleomycin-challenged mice, NEU1 expression is increased significantly with respect to that of the controls, affecting gene expression profiles in lung microvascular endothelial cells." (PMID 39194692, 2024). "For bleomycin-induced pulmonary fibrosis in mice, the selective NEU1 inhibitor C9-butyl-amide-DANA (C9-BA-DANA) strongly reduces the lung inflammation index and fibrosis index compared with untreated controls." (PMID 39194692, 2024). "Previous study demonstrated that Neu1 was upregulated in lung tissues of patients with pulmonary fibrosis, and that inhibition of Neu1 reduced lung fibrosis in a mouse model of the disease." (PMID 38500102, 2024). "Specifically, we want to highlight glycan-regulating proteins linked to macrophages, which hold promise as therapeutic targets in pulmonary fibrosis and sarcoidosis using as examples fucosyltransferases (FUTs), neuraminidase-1 (NEU1), and chitinase-1 (CHIT1)." (PMID 38550597, 2024). "NEU1 has also been found to be a positive regulator of lymphocyte infiltration in pulmonary fibrosis models." (PMID 35281276, 2022). "However, the expression of NEU1 in the fibroblasts of patients with pulmonary fibrosis was decreased in another publication." (PMID 36973294, 2023). "Taken together, these results indicated that NEU1 plays a central role in the pathogenesis of pulmonary fibrosis and NEU1-selective inhibition may offer a potential therapeutic intervention for pulmonary fibrotic diseases." (PMID 35479093, 2022). "We also observed increased NEU1 in mouse pulmonary fibrosis, and in one of three ILD patients." (PMID 29118338, 2017). "The preponderance of evidence demonstrated that elevated NEU1 expression regulated the desialylation and activity of receptors (such as platelet-derived growth factor receptor and Toll like receptors) in epithelial and endothelial cells involved in the development of pulmonary fibrosis." (PMID 38500102, 2024). "Increased expression of NEU1 is observed in the lungs of patients with IPF, and NEU1 participates in the pathogenesis of lung fibrosis by provoking lymphocytic infiltration and promoting accumulation of glycoprotein TGFβ, type I and III collagen." (PMID 38550597, 2024). "Most recent study presents NEU1-selective inhibitor, C9-BA-DANA, mimetic of sialic acid, that dose-dependently inhibited bleomycin-induced lung fibrosis in mouse models, presenting its therapeutic potential for IPF patients." (PMID 38550597, 2024). "Nevertheless, the role of Neu1 in idiopathic pulmonary fibrosis (IPF) is contradictory because one study showed Neu1 upregulation in lung samples from IPF patients, while another study showed Neu1 downregulation." (PMID 39346907, 2024). "A recent report also found increased levels of NEU1 in lung fibroblasts of some but not all pulmonary fibrosis patients, and that adenoviral administration of NEU1 promoted bleomycin-induced lung inflammation and fibrosis." (PMID 29118338, 2017). "A recent report found increased levels of NEU1 in lung fibroblasts of some but not all pulmonary fibrosis patients." (PMID 29118338, 2017).
Obesity (7 papers, 2021 to 2025). Accumulation of substantial excess body fat. "A study examining different mouse models of obesity demonstrated that acidic sialidase activity, corresponding to lysosomal NEU1, is aberrantly regulated across multiple tissues in obese mice." (PMID 41301440, 2025). "NEU1’s involvement in several metabolic diseases has been reviewed previously, highlighting its complex regulatory effects on insulin signaling, obesity, and non-alcoholic fatty liver disease (NAFLD)." (PMID 41301440, 2025). "Co-administration of acacetin and miR-23b-3p restored the obesity-related downregulated levels of NEU1, while NEU1 overexpression offset the effects of miR-23b-3p on the Treg/Th17 cell ratio." (PMID 35479093, 2022). "Upregulation of miR-23b-3p offset the effects of acacetin on obesity-induced IR through regulating Treg/Th17 cell balance via targeting NEU1.The present findings provide a possible prevention strategy for obesity-induced IR." (PMID 33781239, 2021). "We set out to uncover the roles and biological functions of miR-23b-3p and NEU1 in obesity-induced IR, hoping to find a possible prevention against obesity-induced IR in clinical practice." (PMID 33781239, 2021). "In the present study, we confirmed that NEU1 was the target of miR-23b-3p, and that acacetin upregulated the NEU1 expression by downregulating miR-23b-3p expression in mice with obesity-induced IR." (PMID 33781239, 2021). "In conclusion, our study supports a new evidence of the role of acacetin in obesity-induced IR through regulating Treg/Th17 balance via targeting miR-23b-3p/NEU1 axis." (PMID 33781239, 2021). "Collectively, we demonstrated that acacetin ameliorates obesity-induced IR through regulating Treg/Th17 balance via miR-23b-3p/NEU1 axis." (PMID 33781239, 2021). "Our data suggest that neuraminidase Neu1-expressing macrophages in the VAT may be a putative source of NANA in obesity." (PMID 36894557, 2023). "Finally, to confirm the roles and effects of miR-23b-3p and NEU1 in mice with obesity-induced IR, we performed glucose and insulin tolerance tests." (PMID 33781239, 2021). "Moreover, overexpressed NEU1 abrogated the functions of miR-23b-3p on inflammatory cytokines levels in obesity-mediated IR mice (, P < 0.05)." (PMID 33781239, 2021). "Furthermore, upregulated miR-23b-3p abrogated the effects of acacetin on miR-23b-3p and NEU1 expressions in mice with obesity-induced IR (P < 0.001)." (PMID 33781239, 2021). "Previous study indicated that NEU1 may be the target of miR-125b, but the relationship between NEU1 and miR-23b-3p in obesity-mediated IR still needed to be addressed." (PMID 33781239, 2021). "In addition, in obesity-induced IR mice, we observed that upregulating miR-23b-3p further enhanced the effects of obesity-induced IR on the levels of inflammatory cytokines, but overexpressed NEU1 reduced levels of inflammatory cytokines (, P < 0.05)." (PMID 33781239, 2021). "Therefore, accumulation of Neu1-expressing VAT macrophages in obesity may contribute to chronic local inflammation, which may in turn negatively affect systemic immunity." (PMID 36894557, 2023). "However, following NEU1 overexpression, the body weight and fat percent of the mice with obesity-induced IR were reduced, and overexpressed NEU1 could reverse the effects of upregulating miR-23b-3p (P < 0.01)." (PMID 33781239, 2021). "Moreover, we also observed that miR-23b-3p upregulation repressed NEU1 expression in mice with obesity-induced IR, indicating that upregulated miR-23b-3p might enhance obesity-induced IR through regulating Treg/Th17 balance via targeting NEU1." (PMID 33781239, 2021). "To confirm the role and effects of NEU1 and miR-23b-3p on mice with obesity-induced IR, we first measured the body weight and fat percent of the mice following the model construction and injection of lentivirus carriers for miR-23b-3p mimic and NEU1 overexpression plasmid." (PMID 33781239, 2021).
Obesity (continued). "However, relationship between miR-23b-3p and NEU1 in obesity-induced IR is less discussed." (PMID 33781239, 2021). "We also found that overexpressed NEU1 reduced AUC of OGTT and ITT and reversed the effects of miR-23b-3p on the AUC of OGTT and ITT of obesity-induced IR mice (P < 0.05)." (PMID 33781239, 2021). "As such, targeting neuraminidases, particularly NEU1, NEU2, and NEU3, may offer novel therapeutic strategies for obesity, type 2 diabetes, and NAFLD." (PMID 41301440, 2025). "Besides, NEU1 overexpression abrogated the effects of miR-23b-3p on FBG and FI levels in the mice with obesity-induced IR (P < 0.01)." (PMID 33781239, 2021). "After acacetin injection, obesity-induced IR model was constructed with or without miR-23b-3p upregulation and Neuraminidase 1 (NEU1) overexpression in mice." (PMID 33781239, 2021). "In our study, upregulated NEU1 offset the effects of miR-23b-3p on body weight, fat percent, FBG, FI and AUC of both OGTT and ITT, and inflammatory factors (CRP, IL-6, TNF-α, MCP1) in mice with obesity-induced IR." (PMID 33781239, 2021).
COVID-19 (6 papers, 2021 to 2025). A disease caused by infection with severe acute respiratory syndrome coronavirus 2. "In addition, some patients recovered from COVID-19 didn’t produce detectable neutralizing antibodies, whether this phenotype is associated the immune dysfunction caused by NEU1 deficiency in cellular response, we should learn it more accurately and deeply." (PMID 38500102, 2024). "NEU1 has been proposed as a potential therapeutic target for COVID-19, and against viral pathogens in future coronavirus pandemics, on the basis that NEU1 inhibitors can limit SARS-CoV-2 replication in COVID-19 patients." (PMID 39194692, 2024). "Recent studied revealed that host NEU1 interplay with MMP-9 caused neutrophil overactivation by shedding Sia during severe infections including in sepsis and COVID-19." (PMID 38500102, 2024). "However, it is important to note that the role of NEU1 in COVID-19 is still not fully understood and further research is needed to elucidate its precise mechanisms and implications in the disease." (PMID 38500102, 2024). "In this work, we identified an increased expression of lysosomal genes such as LAMTOR1, NEU1, GBA1, BORCS8, and BLOC1S1 in severe COVID-19 patients." (PMID 38262689, 2024). "Abnormally high expression of NEU1 interacted with MMP-9, contributed to neutrophil overactivation from COVID-19 patients with severe infections." (PMID 38500102, 2024). "One study showed that the neuraminidase-1 enzyme in human cells may be important in the SARS-CoV-2 entry into host cells, and so oseltamivir may instead act as a host-targeting agent when used to treat COVID-19." (PMID 41422204, 2025).
lupus (6 papers, 2013 to 2024). "Of translational interest, the human NEU1 gene is located on chromosome 6 within the strongest genetic risk factor loci for lupus, the HLA region." (PMID 24040398, 2013). "NEU1 activity promotes IL-6 secretion from lupus-prone MRL/lpr primary mouse mesangial cells (MCs) in response to an IgG mimic, and to circulating lupus factors through the TLR4-MAPK p38 or ERK signaling pathway." (PMID 39194692, 2024). "The higher ST6Gal-1 level and ST6Gal-1/Neu1 ratio in B cells potentially suggest greater lupus activity, due to their compatibility with low complement levels, pending for a large-population study to support it." (PMID 26981635, 2016). "More specifically, NEU1 expression and catalytic activity were increased in the kidneys of MRL/lpr lupus mice, and kidney mesangial cells from NEU1-haplodeficent mice had reduced cytokine expression and secretion in response to LPS or lupus serum (LS) compared with NEU1-expressing mice." (PMID 35479093, 2022). "Interestingly, a complete knockout of NEU1 in the C57BL/6 strain resulted in pathological effects similar to those observed in lupus, including splenomegaly and proteinuria." (PMID 32187230, 2020). "Similarly, no study has been done to explore possible relationship between Neu1 and Neu3 on lupus blood cells and lupus disease activity." (PMID 26981635, 2016). "Hence, ST6Gal-1 and Neu1 levels, and ST6Gal-1/Neu1 ratios were paralleled in various blood cells from individual lupus patients." (PMID 26981635, 2016). "Third, B-cell ST6Gal-1 levels and ST6Gal-1/Neu1 ratios may indicate the presence of lupus activity pending further exploration, due to the correlations of these variables with low serum C3c and C4 levels." (PMID 26981635, 2016). "Together, our results in the T cells from early disease lupus mice suggest FLI1 controls directly or indirectly the transcription of Neu1 such that reduction of FLI1 leads to decreased Neu1 expression/activity leading to decreased TCR-specific activation and IL-4 production." (PMID 24040398, 2013). "In vitro, although renal NEU1 is primarily responsible for mediating cytokine release from MCs, it may not be involved in regulating renal glycosphingolipid (GSL) levels in vivo or influencing the pathogenesis of nephritis in lupus-susceptible mice." (PMID 39194692, 2024). "In summary, our results demonstrate a role for FLI1 in regulating lupus T cell activation and IL-4 production through modulation of glycosphingolipid metabolism, specifically by mediating the breakdown pathway through the control of Neu1 expression and/or NEU activity during early disease." (PMID 24040398, 2013). "Fourth, the positive correlations of ST6Gal-1 and Neu1 levels on B, T, and PMN cells and monocytes in lupus, both overall and in individuals, is likely a new finding with unexplained reasons." (PMID 26981635, 2016). "NEU1 and NEU3 protein expression within the kidney has not been analyzed in detail; however, we demonstrated NEU1 and NEU3 expression in the glomeruli of mouse renal sections appear to be higher in lupus mice with nephritis compared to lupus mice without nephritis." (PMID 32187230, 2020).
myocardial infarction (6 papers, 2022 to 2025). Gross necrosis of the myocardium, as a result of interruption of the blood supply to the area, as in coronary thrombosis. "Previous studies have shown that elevated NEU1 expression in myocardial infarction tissues leads to inhibition of the SIRT1/PGC-1α pathway, thereby leading to altered mitochondrial function causing cardiac dysfunction." (PMID 40221400, 2025). "NEU1 expression was increased in human circulating monocytes isolated from patients with myocardial infarction compared with healthy controls, and high NEU1 levels were observed in macrophages isolated from atherosclerotic plaques." (PMID 35479093, 2022). "The purpose of this study was to investigate the functions and possible mechanisms of NEU1 in myocardial remodeling and mitochondrial metabolism induced by myocardial infarction (MI)." (PMID 35548408, 2022). "In the mononuclear blood cells of patients with myocardial infarction, the expression of NEU1 increased compared with healthy controls." (PMID 35002528, 2022). "Functional metabolomics have also been used to identify a key role for Neu5Ac in acute myocardial infarction, which led to the suggestion that neuraminidase-1 may represent a therapeutic target for CAD." (PMID 36545018, 2022). "NEU1 inhibition opens up a whole new field of treatment after myocardial infarction." (PMID 35548408, 2022). "Indeed, serum NEU1 levels are elevated in patients with acute myocardial infarction." (PMID 39194692, 2024). "NEU1 expression is characteristically upregulated in myocardial infarction (MI) tissues, and is reportedly higher in the mononuclear blood cells of MI patients vis-à-vis healthy controls." (PMID 39194692, 2024).